CDKL5 (cyclin dependent kinase like 5)
Diseases named in the same sentence as CDKL5 in open-access papers (continued):
Sharing a sentence is not in itself a finding about the gene and the disease.
Epileptic encephalopathy (continued). "Cyclin‐dependent kinase‐like 5 (CDKL5) deficiency disorder (CDD) is a developmental and epileptic encephalopathy caused by variants in the CDKL5 gene." (PMID 38450883, 2024). "The core features of CDKL5-related phenotype are an early onset epileptic encephalopathy, severe developmental delay, deceleration of head growth, impaired communication, hand stereotypies and pronounced hypotonia." (PMID 38612920, 2024). "The clinical findings, along with the EEG pattern, were suggestive of a CDKL5-related epileptic encephalopathy." (PMID 39000022, 2024). "This Italian multi-center observational study focused on 34 patients with CDKL5-related epileptic encephalopathy, aiming to enhance the understanding of the clinical and molecular aspects of CDD." (PMID 38874638, 2024). "Here the authors show that a model of CDKL5 deficiency disorder involves a channelopathy of CACNA1E gain-of-function, molecularly linking two distinct single-gene developmental and epileptic encephalopathies." (PMID 38081835, 2023). "Mutations in the cyclin-dependent kinase-like 5 gene (CDKL5, OMIM 300203) have been described in CDKL5-related disorders including early-onset seizure variant of rett syndrome and early-onset epileptic encephalopathies." (PMID 24564546, 2014). "Accumulated evidence show that phenotype of CDKL5-related disorders overlaps with early-onset seizure variant of RTT (RTT, OMIM 312750) and early-onset epileptic encephalopathies with X-linked infantile spasms (ISSX,OMIM308350)." (PMID 24564546, 2014). "Mutations in CDKL5 gene are responsible for 7 with Hanefeld variants of RTT and 2 with early-onset epileptic encephalopathy in 71 girls as well as for 1 infantile spasms in 31 males." (PMID 24564546, 2014). "However, CDKL5 mutations have been described in early-onset seizure variants of RTT and early-onset epileptic encephalopathies." (PMID 38540345, 2024). "Among these 11 patients, 3 patients relapsed from not taking the medication irregularly, 2 patients harbored gene mutations (CDKL5 and KCNT1) associated with epileptic encephalopathy, and the remaining 6 patients had abnormal findings on brain MRI (e.g., encephalomalacia and pachygyria)." (PMID 37217894, 2023). "Thus, our results establish Cav2.3 overactivity as a common feature of CACNA1E (DEE69) and CDKL5 (DEE2) epileptic encephalopathies, potentially explaining some of the overlapping clinical features of these diseases." (PMID 38081835, 2023). "CDKL5 deficiency disorder is a debilitating developmental and epileptic encephalopathy for which no targeted treatment exists." (PMID 35974796, 2022). "CDKL5 deficiency disorder is a drug-resistant epileptic encephalopathy and currently no approved therapies are available for its treatment." (PMID 35665761, 2022). "Therefore, our findings regarding these genes are consistent with those of previous studies and confirm that patients with epileptic encephalopathy with SCN1A and SCN2A mutations respond well to KD, while patients with CDKL5 mutations respond poorly to KD." (PMID 30061856, 2018). "Among the ten patients with CDKL5 gene mutation in the cohort, phenotype consisted of 7 females with Hanefeld variant of RTT, 1 male with infantile spasms and 2 females with early onset epileptic encephalopathy at the first referral." (PMID 24564546, 2014).
Epileptic encephalopathy (continued). "Therefore, in the last years, CDKL5 screenings have been extended to cohorts of both genders in which patients were characterized by epileptic encephalopathy." (PMID 22779007, 2012). "Herein, we report a 3-year-old girl presenting with an epileptic encephalopathy, highly suggestive of CDD, and harboring a pericentric de novo inversion on chromosome X, disrupting the CDKL5 coding sequence." (PMID 39000022, 2024). "Among these, CDKL5 is of particular interest because of its involvement in CDKL5 deficiency disorder (CDD), a rare epileptic encephalopathy with several comorbidities for which there are no specific treatments." (PMID 40371392, 2025).
infantile spasms (29 papers, 2012 to 2025). A rare epilepsy syndrome characterized by onset of epileptic spasms in infants between 2 and 12 months of age, and rarely up to 24 months. "Mutations in the X-linked cyclin-dependent kinase like 5 (CDKL5, OMIM 300203) gene (previously known as STK9, serine/threonine kinase 9) are responsible for a severe encephalopathy with X-linked infantile spasms (ISSX, OMIM 308350)." (PMID 38612920, 2024). "It was at this time that CDKL5 was reported as the second cause of X-linked infantile spasms (ISSX), for the first time highlighting genetic heterogeneity in this clinical syndrome." (PMID 35795799, 2022). "The early seizure variant (Hanefeld variant), associated with CDKL5 mutations, is characterized by seizure onset before 5 months of age, usually with infantile spasms (50%) and refractory myoclonic epilepsy (25%)." (PMID 30929312, 2019). "Among 67 West syndrome patients, pathogenic mutations were found in 20 (29.9%) patients, including 9 patients with CDKL5 mutations." (PMID 30061856, 2018). "Mutations in the X-linked Cyclin-Dependent Kinase-Like 5 gene (CDKL5) cause early onset infantile spasms and subsequent severe developmental delay in affected children." (PMID 27315173, 2016). "Among the patients with CDKL5 gene mutations, 2 are diagnosed with early onset epileptic encephalopathy, 1 with infantile spasms and 7 with early-onset seizure of RTT syndrome when they were first referred to the clinician." (PMID 24564546, 2014). "Although the 126 AA location change to Trp(c.378C > G (p.Cys126Trp)) of CDKL5 can be observed in other infantile spasm patients in Clinvar, in our patient 2, the 377 base mutation (c.377G > T) translated to 126 Phe (p.Cys126Phe), is the first report to our knowledge." (PMID 32111237, 2020). "CDKL5 deficiency disorder (CDD) is a rare and X-linked dominant condition, with many aliases, including Developmental Epileptic Encephalopathy 2 (DEE2)." (PMID 35795799, 2022). "All male CDKL5 mutation-positive cases had been classified as having an EIEE, presenting with seizures including infantile spasms aged 3 weeks and had severe or profound developmental delay." (PMID 26993267, 2016). "Kalscheuer reported two unrelated girls with infantile spasms and mental retardation whose CDKL5 gene were disrupted by different balanced X-autosome translocations in 2003." (PMID 24564546, 2014). "The cyclin-dependent kinase-like 5 gene (CDKL5) is located in the Xp22 region and has been found to be associated with atypical RTT with infantile spasms or early seizures starting in the first postnatal months (Hanefeld variant)." (PMID 22867051, 2012). "Responder rate of West syndrome patients with CDKL5 mutations was significantly lower than responder rate of West syndrome patients without CDKL5 mutations (0.0 vs. 41.4%, p = 0.021)." (PMID 30061856, 2018). "Among patients with West syndrome, patients with CDKL5 mutations showed a significantly poorer response to KD than other West syndrome patients without CDKL5 mutation." (PMID 30061856, 2018).
infantile spasms (continued). "Mutations in the X-linked Cyclin-Dependent Kinase-Like 5 gene, CDKL5 (Mendelian Inheritance in Man, MIM: 300203; previously known as STK9), cause a range of phenotypes, including EIEE2 (MIM: 300672), a form of early infantile epileptic encephalopathy, and infantile spasms." (PMID 27315173, 2016).
Dravet syndrome (19 papers, 2009 to 2026). "Further, it is also an approved drug by USFDA in treating conditions such as idiopathic epilepsy, CDKL5 deficiency, resistant Lennox–Gastaut syndrome, Dravet syndrome, and tuberous sclerosis complex." (PMID 36671547, 2023). "Ataluren was not an effective treatment for seizures in children suffering from nonsense variants of Dravet syndrome (DS) or CDKL5 Deficiency Syndrome (CDD)." (PMID 34451881, 2021). "Another drug used as a possible treatment for seizures involving Dravet syndrome and CDKL5 deficiency disorder is ataluren, a drug whose main action is for preterm infants, allowing for the reading of the ribosome of an mRNA with the para codon generated in a full-length protein." (PMID 38248286, 2024). "The onset of severe, drug‐resistant seizures in early childhood is characteristic of the rare epileptic disorders Lennox‐Gastaut syndrome, Dravet syndrome, and CDKL5 deficiency disorder and is frequently observed in the rare genetic conditions tuberous sclerosis complex and Rett syndrome." (PMID 35765698, 2022). "Due to the good readthrough activity in preclinical studies and the low toxicity, ataluren was further tested in human clinical trials, including CF, DMD, Dravet Syndrome (DS), CDKL5 Deficiency Syndrome (CDD), and aniridia." (PMID 37371567, 2023). "Dravet syndrome (DS), Lennox‐Gastaut syndrome (LGS), and CDKL5 deficiency disorder (CDD) are rare, severe, treatment‐resistant developmental and epileptic encephalopathies with distinct etiologies." (PMID 35765698, 2022). "In clinical trials, FFA has shown efficacy for treatment of seizures associated with Dravet syndrome (DS), Lennox‐Gastaut syndrome (LGS), and CDKL5 deficiency disorder (CDD)." (PMID 35599345, 2022). "However, a phase 2 clinical trial of non-aminoglycoside drug, Ataluren, was recently showed to be not effective for the treatment of nonsense mutations in CDKL5 deficiency disorder (CDD) and Dravet syndrome (DS)." (PMID 37304036, 2023).
developmental delay (18 papers, 2012 to 2026). "CDKL5 Deficiency Disorder (CDD) is a severe neurodevelopmental disorder caused by mutations in the X-linked CDKL5 gene, resulting in early-onset seizures, developmental delays, and cognitive and sensorimotor impairments." (PMID 40903342, 2025). "CDKL5 deficiency disorder is caused by CDKL5 variants and is characterized by drug-resistant seizures and global developmental delay." (PMID 36119689, 2022). "Genetic variants in CDKL5 cause a disorder that is characterized by early onset seizures and subsequent significant developmental delay." (PMID 32722525, 2020). "CDKL5 deficiency disorder is an X‐linked neurodevelopmental encephalopathy caused by mutations in the CDKL5 gene characterised by early‐onset, refractory epilepsy, and cognitive and motor developmental delays." (PMID 34495563, 2022). "All the patients with CDKL5 mutation showed severe psychmotor developmental delay." (PMID 24564546, 2014). "Cyclin-dependent kinase-like 5 deficiency disorder (CDD) is a neurodevelopmental condition characterized by infantile-onset epilepsy, developmental delay, intellectual and motor disabilities, sleep disturbances, and cortical visual impairment." (PMID 41230376, 2025). "Unlike RTT, in CDKL5-deficiency disorder, developmental delay is present from birth, and the seizures begin far earlier (<3 months)." (PMID 40508170, 2025).
developmental and epileptic encephalopathy (15 papers, 2019 to 2026). An epilepsy associated with developmental impairment that may be due to either the underlying etiology or the superimposed epileptic activity, or both. "Cyclin-Dependent Kinase-Like 5 (CDKL5) Deficient Disorder (CDD) is a rare X-linked developmental and epileptic encephalopathy characterized by early-onset refractory epilepsy, severe neurodevelopmental impairment, and lifelong disability." (PMID 42194004, 2026). "Cyclin-dependent kinase-like 5 (CDKL5) deficiency disorder (CDD) is an ultrarare genetic condition causing developmental epileptic encephalopathy characterized by seizures and motor and intellectual disabilities." (PMID 40493384, 2025). "CDKL5 deficiency disorder (CDD) is a rare developmental epileptic encephalopathy (DEE) caused by mutations in cyclin-dependent kinase-like 5 (CDKL5)." (PMID 41301530, 2025). "CDKL5 deficiency disorder (CDD) is a rare Developmental and Epileptic Encephalopathy (DEE) caused by a genetic variant in CDKL5." (PMID 41364294, 2025). "Recently, we proposed the homozygous cdkl5sa21938 mutant zebrafish as a model of CDKL5 deficiency disorder (CDD), a developmental epileptic encephalopathy with diverse symptoms." (PMID 40649845, 2025). "Disruption of CDKL5, resulting in decreased activity, leads to CDKL5 deficiency disorder (CDD), a rare and severe condition classified as a developmental epileptic encephalopathy." (PMID 40649845, 2025). "CDKL5-related developmental epileptic encephalopathy represents a severe and complex disorder." (PMID 42261526, 2026). "To tackle this question, we used a model of CDKL5 Deficiency Disorder (CDD), a rare developmental epileptic encephalopathy caused by de novo mutations on the X-linked autism-related Cyclin-dependent kinase-like 5 (CDKL5) gene affecting female and male individuals." (PMID 36737483, 2024). "Furthermore, in a female patient (E49) with developmental and epileptic encephalopathy characterized by seizures of various types, starting at 7 weeks of age and resistant to antiseizure medication, we identified a deletion of exons 4–18 in the CDKL5 gene." (PMID 38328757, 2023).
Encephalopathy (13 papers, 2012 to 2025). Encephalopathy is a term that means brain disease, damage, or malfunction. "Peculiar seizures with spasms starting in SWS are an early diagnostic clue in infants with CDKL5 encephalopathy." (PMID 37193389, 2022). "Early-onset spasms starting from SWS have never been identified as a specific diagnostic clue in infants with CDKL5 encephalopathy." (PMID 37193389, 2022). "This series shows that, based on the semiology of terror-associated spasms, CDKL5 encephalopathy could be recognized very early in the course of the disease." (PMID 37193389, 2022). "Other authors have speculated that the variable clinical presentations of CDKL5-related encephalopathy result from the transcriptional or translational effects of CDKL5 mutations." (PMID 22867051, 2012). "Cyclin-dependent kinase-like 5 (CDKL5, OMIM:300203, 300672) deficiency disorder (CDD, OMIM #300203) is a rare encephalopathy that affects between 1:40 000 to 1:60 000 newborns, with females making up about 90 percent of diagnosed patients." (PMID 39583831, 2024). "The combination of spasms and myoclonus is another striking ictal feature in CDKL5 encephalopathy that persists throughout the course of the disease." (PMID 37193389, 2022). "An early diagnosis of CDKL5 encephalopathy is clinically feasible based on the discrete characteristics of sleep-related seizures." (PMID 37193389, 2022). "Glutamatergic excitatory neurotransmission is upregulated in CDKL5 encephalopathy, due to both alpha-amino-3-hydroxy-5-methyl-4-isoxazolepropionic acid (AMPA) receptor dysregulation and GluN2B NMDA-receptor (NMDA-R) subunit overexpression." (PMID 37193389, 2022). "Their characteristics suggest CDKL5 encephalopathy, which enables a selective targeting of this gene, thereby saving precious weeks or months of searching." (PMID 37193389, 2022). "In contrast, seizures in CDKL5 encephalopathy typically start in QS or SWS, accompanied by stark terror and screaming until brisk movements upper limbs allow to recognize the spasms." (PMID 37193389, 2022). "Patients with CDKL5 encephalopathy (n = 10, responder rate = 0.0%, p = 0.031) showed significantly less-favorable responses to KD." (PMID 30061856, 2018). "A common mechanism in CDKL5 encephalopathy and night terror can be suspected." (PMID 37193389, 2022). "Furthermore, in patients with CDKL5 encephalopathy, seizures mainly in sleep have been reported in a few cases whereas the link with SWS has not been mentioned nor have spasms linked to sleep terror-like events." (PMID 37193389, 2022). "For instance, a hemizygous de novo 2.8-Mb microdeletion Xp22.2–Xp22.13 was described, including the CDKL5 and NHS genes, both contributing to the associated phenotypic presentation of severe encephalopathy, congenital cataracts, and tetralogy of Fallot in a 10-month-old boy." (PMID 34884523, 2021).
autism (12 papers, 2012 to 2025). Persistent deficits in social interaction and communication and interaction as well as a markedly restricted repertoire of activity and interest as well as repetitive patterns of behavior. "Several of these genes have strong or suggestive associations with autism, according to their SFARI scores (e.g., EIF4E–Score 2; CDKL5-Score 1S)." (PMID 41367385, 2025). "Moreover, pathological mutations in DYRK1A cause phenotypic outcomes (autism, seizures, cognitive impairment) and molecular defects (neural progenitor proliferation, microtubule dynamics, dendritic development, spine maturation) that greatly overlap with those linked to CDKL5." (PMID 32032735, 2020). "Most notably, patient M01813 carried LGD DNMs in autism risk genes SCN2A and CDKL5, albeit the latter occurs near the terminal portion of the protein." (PMID 30564305, 2018). "Interestingly, of the autism genes positively correlated with δ-catenin, there is a significant enrichment in genes involved in dendrite morphogenesis, including PDLIM5, SHANK1, CDKL5, and DLG4." (PMID 27822498, 2016).